ALDOA (aldolase, fructose-bisphosphate A)
Diseases named in the same sentence as ALDOA in open-access papers (continued):
Sharing a sentence is not in itself a finding about the gene and the disease.
cancer (continued). "ALDOA lactylation at the K230 and K322 sites causes DDX17 release from ALDOA, allowing DDX17 entry into the nucleus and binding to SRY-box transcription factor 2 (SOX2) to activate their target genes to maintain cancer cell stemness." (PMID 40333742, 2025). "ALDOA is a crucial glycolytic enzyme that is often aberrantly expressed in cancer cells, contributing to the Warburg effect." (PMID 39099416, 2024). "Cancer cells take up glucose and supply their energy requirements through anaerobic glycolysis; in these cells, ALDOA is overexpressed." (PMID 38792037, 2024). "ALDOA is predominantly expressed in muscle and red blood cells, and its aberrant expression drives the pathogenesis of various cancers." (PMID 37431681, 2023). "ALDOA is an enzyme essential for glycolysis and glucose homeostasis, and it is highly expressed in numerous human cancers, including GC." (PMID 37403106, 2023). "As has been reported previously, several signaling pathways are involved in ALDOA-mediated cancer development." (PMID 37403106, 2023). "ALDOA protein expression is upregulated in many cancers and this upregulation is likely to be critical for the metabolic reprogramming observed in tumours." (PMID 37704669, 2023). "ALDOA, the most abundant aldolase isoform in cancers, plays a key role in glycolysis and gluconeogenesis." (PMID 36732657, 2023). "Aldolase A (ALDOA), a crucial glycolytic enzyme, is often aberrantly expressed in various types of cancer." (PMID 37431681, 2023). "Further investigation is required to analyse the feasibility of cancer-targeting strategies that inhibit ALDOA in combination with genotoxic therapies." (PMID 37704669, 2023). "Since ALDOA is reported in several cancer studies, we first analyzed the overall expression levels of ALDOA mRNA in different tumors compared to normal by Oncomine." (PMID 35804089, 2022). "We and other researchers have found that ALDOA expression is related to the poor prognosis of many cancers, including lung, liver, pancreatic, colorectal, stomach, bladder, renal, and bone sarcomas." (PMID 35404841, 2022). "Here, we describe the prognostic value of ALDOA in pan-cancer and report its immunological correlation with different cancers." (PMID 35804089, 2022). "This study explored the relationship between FBP1 and ALDOA across cancers and identified a significant correlation between LIHC and LUAD." (PMID 35404841, 2022). "We collected 100 genes related to ALDOA expression in pan-cancer using GEPIA2, and obtained the first 6 most closely related genes." (PMID 35804089, 2022). "Based on this comprehensive analysis, we believed that ALDOA can be used as a prognosis biomarker in pan-cancer and is related to immune infiltration." (PMID 35804089, 2022). "As the downstream target of miR-335-5p, ALDOA promotes human cancer progression by accelerating the glycolysis rate." (PMID 36030248, 2022). "The function of miR-122 and its associated mRNAs such as TRIM29, Bcl-W, CCNG1, CDC25A, XIAP, and ALDOA are reportedly downregulated during cancer cell progression." (PMID 36499586, 2022). "Both ALDOA and OCT4 are metabolic proteins associated with glucose intake and are crucial for cancer progression." (PMID 36052282, 2022). "Increased expression of ALDOA and decreased expression of FBP1 are associated with the progression of various forms of cancer in humans." (PMID 35404841, 2022). "To investigate the relationship between FBP1 and ALDOA among cancers, we screened for prognostic value and candidate gene expression across cancers." (PMID 35404841, 2022). "In this study, the overall roles of ALDOA in pan-cancer have been investigated from several aspects using databases and online analysis tools." (PMID 35804089, 2022). "Recent studies have demonstrated that the key enzyme ALDOA (aldolase A) in glycolysis is a cancer-related gene according to the Human Protein Atlas information." (PMID 35741857, 2022).
cancer (continued). "One identified protein was aldolase A (ALDOA), which is associated with HIF signaling and poor prognosis in human carcinomas." (PMID 35236823, 2022). "Another compound, “UM0112176”, emulates raltegravir’s mechanism of disrupting ALDOA interaction with actin, disrupting the cytoskeleton and initiating a cascade of intracellular events leading to cancer cell apoptosis." (PMID 34458323, 2021). "MSPA also inhibited cancer cell proliferation and induced apoptosis by inhibiting critical enzymes involved in the Warburg effect: aldolase A (ALDOA), enolase 1 (ENO1), and fumarate hydratase (FH)." (PMID 34681284, 2021). "ALDOA is an important enzyme involved in the glycolysis pathway that is highly expressed in a wide range of cancers." (PMID 33858449, 2021). "The aberrant expression of miR-122 has been indicated to be involved in cancer cells proliferation and invasion by inhibiting the expression of fructose-bisphosphate A aldolase (ALDOA)." (PMID 33439933, 2021). "ALDOA expresses fructose-bisphosphate aldolase A, which is involved in glycolysis and gluconeogenesis, and is also overexpressed in cancer." (PMID 35222014, 2021). "The results of our study revealed novel functional roles of ALDOA in inducing cancer stemness via the inhibition of miR-145 expression and the activation of Oct4 transcription." (PMID 32188842, 2020). "Muscle fructose-1,6-bisphosphate aldolase (ALDOA) is among the most abundant glycolytic enzymes in all cancer cells." (PMID 31558701, 2019). "In a genome-wide siRNA screen for senescence regulators, we recently identified ALDOA as a strong candidate for inhibition to induce accelerated senescence in cancer cells." (PMID 31401411, 2019). "Unexpectedly, UM0112176 treatment also resulted in the depletion of ALDOA from nuclei of cancer cells." (PMID 31558701, 2019). "The overexpression of ALDOA in cancer cells represents a mechanism by which metastatic cancer cells ensure integrity of their actin cytoskeleton while undergoing the epithelial–mesenchymal transition." (PMID 31558701, 2019). "The inhibition of ALDOA was shown to break the feed-forward loop of glycolysis to inhibit the proliferation of cancer cells." (PMID 31558821, 2019). "It would be interesting to further determine the possible roles of the DIO3OS/miR-122/ALDOA axis in regulating glycolysis and cancer progression in PC." (PMID 31384177, 2019). "Research has repeatedly shown that ALDOA is overexpressed in various types of cancers including pancreatic cancer, hepatocellular carcinoma, colorectal cancer and lung cancer." (PMID 29764507, 2018). "The ubiquitous overexpression of ALDOA in all of the 100 patients studied supports the relevance of this increased expression in driving or sustaining elevated proliferation rhythm in cancer." (PMID 28686225, 2017). "Additionally, knocking down ALDOA in SKBR3 cells blocked cells at G0/G1 under minimized glycolytic condition, suggesting that ALDOA could contribute to the progress of cancer, at least partially through its association with genes relevant to cell cycle independent of glycolysis." (PMID 28191039, 2017). "Our study has displayed ALDOA mRNA upregulation in cancers, confirmed its seemingly universal effect on carcinogenesis." (PMID 28191039, 2017). "AA genes plus ALDOA represent a potential new signature for development and prognosis in several cancers." (PMID 28191039, 2017). "Specifically, significant decreases in expression of HMOX1 (−50-fold, p = 0.03) and aldolase (ALDOA; −500-fold, p = 0.01) were observed in CD49fhiCD24hi cancer cells compared with benign cell counterparts." (PMID 26316122, 2015). "The relative expression values of ALDOA were 0.87±0.47 in carcinoma tissues and 0.54±0.27 in normal tissues, respectively." (PMID 24465716, 2014). "Cellular metabolism and transportation related genes (ALDOA, SLC16A3, TPI1, LDHB, KCNQ5, and PGM1), which are implicated in human cancer, also remained upregulated even 2-month after radiation exposure." (PMID 23216862, 2012).
cancer (continued). "Targeting ALDOA presents an opportunity to overcome the inherent metabolic plasticity of cancer cells, as it not only removes the ability of cells to utilize glycolysis as an energy-generating pathway but converts glycolysis into a trap for high-energy phosphate." (PMID 39833612, 2025). "Thus, our findings indicate that induction of imbalanced glycolysis by targeting ALDOA presents a unique opportunity to overcome the inherent metabolic plasticity of cancer cells." (PMID 39833612, 2025). "Therefore, our study aims to systematically investigate ALDOA expression across cancers with a particular focus on its prognostic value and immune-related functions in LUSC." (PMID 41239433, 2025). "The heatmap revealed that ALDOA is highly expressed in macrophages across multiple cancer types." (PMID 41239433, 2025). "Moreover, ALDOA inhibitors selectively promote ferroptosis in cancer cells, both in vitro and in vivo." (PMID 41220277, 2025). "Although it has been demonstrated that ALDOA regulates the cell cycle and migration in various types of cancer, its specific functions in muscle biology, particularly in the determination of the fate of satellite cells, remain unclear." (PMID 41153403, 2025). "ALDOA, an enzyme crucial in glycolysis, is upregulated in various cancers." (PMID 41235096, 2025). "In addition to its glycolytic function, ALDOA has been validated as a candidate oncogenic protein in a variety of cancers." (PMID 39755705, 2025). "Recent studies highlight ALDOA (Aldolase A) as a crucial metabolic enzyme in cancer progression." (PMID 41239433, 2025). "Consequently, the Dio3os/miR-122/ALDOA pathway is a significant focus for exploring the regulation of glycolysis in cancer." (PMID 41235096, 2025). "Our finding that ALDOA is a common essential enzyme in HCC cell lines across different oncogenotypes and during exposure to diverse environmental conditions highlights the high susceptibility of cancer cells to imbalanced glycolysis." (PMID 39833612, 2025). "ALDOA exerts oncogenic activity in cancers via different signaling pathways." (PMID 39755705, 2025). "Together, these results suggest that inducing imbalanced glycolysis by targeting ALDOA could be a therapeutic strategy for cancers that engage in aerobic glycolysis." (PMID 39833612, 2025). "Multiple studies have consistently demonstrated the overexpression of ALDOA in cancer cells." (PMID 40708574, 2025). "Inspired by these findings, our study adopts a pan-cancer framework to first establish the overarching significance of ALDOA, followed by a deep dive into its specific role and mechanism in LUSC, thereby aiming to delineate both its universal and context-dependent oncogenic functions." (PMID 41239433, 2025). "Inducing imbalanced glycolysis by targeting ALDOA could thus be highly efficient in eliminating cancer cells." (PMID 39833612, 2025). "Furthermore, inhibition of ALDOA activity by using a pharmacological inhibitor or silencing leads to the death of cancer cells due to disruption of the integrity of their actin cytoskeleton, which is dependent on aldolase activity." (PMID 37449059, 2023). "report a previously unknown nonenzymatic function of ALDOA in HCC progression and establish the direct linkage between ALDOA and mRNA translation in cancer." (PMID 37431681, 2023). "Five enzymes involved in glycolysis present only or mainly in sEVs isolated from cancer-derived cell lines were validated: aldolase (ALDOA), glyceraldehyde-3-phosphate dehydrogenase (GAPDH), phosphoglycerate kinase (PGK1), enolase (ENO) and pyruvate kinase (PKM)." (PMID 37189694, 2023). "Although ALDOA has been reported to play additional roles beyond its conventional enzymatic role, its nonmetabolic function and underlying mechanism in cancer progression remain elusive." (PMID 37431681, 2023). "High ALDOA expression predicted poor prognosis in GC and other human cancers." (PMID 37403106, 2023).
cancer (continued). "ALDOA is known to be the most abundant aldolase isoform in almost all cancers." (PMID 37449059, 2023). "Next, we used different databases to analyze the prognostic value of ALDOA in pan-cancer." (PMID 35804089, 2022). "Using the ONCOMINE database, the expression of ALDOA in various cancers was analyzed." (PMID 35804089, 2022). "Numerous studies have established that ALDOA plays a role in cancer initiation and progression." (PMID 36564744, 2022). "Overexpression of ALDOA protein has been observed in several cancers." (PMID 35805203, 2022). "In addition, there is a significant positive correlation between higher ALDOA levels and cancer stages." (PMID 36494481, 2022). "It was found that ALDOA has been identified as an important factor for cancer cell proliferation." (PMID 35711827, 2022). "ALDOA is coding genes of Aldolase A that involves in the glycolysis of cancer cells." (PMID 34595103, 2021). "Some studies also proved that the overexpression of ALDOA might contribute to tumorigenesis and the progression of cancers through modulation of HIF-1α signaling." (PMID 33858449, 2021). "Background: aldolase A (ALDOA) has been reported to be involved in kinds of cancers." (PMID 34925439, 2021). "ALDOA was downregulated in two cancer types, including GBM and PRAD." (PMID 34925439, 2021). "We observed that the wild-type and mutant forms of ALDOA promoted cancer stemness." (PMID 32188842, 2020). "Since ALDOA participates in many cellular events necessary for cancer cell survival and proliferation, we hypothesised that disruption of the moonlighting functions of ALDOA could provide a preferable target for anti-cancer therapy." (PMID 31558701, 2019). "UM0112176 binding to ALDOA was also associated with a significant increase in cellular calcium level in cancer but not in normal cells." (PMID 31558701, 2019). "ALDOA, a glycolytic enzyme that catalyzes the reversible conversion of fructose-1, 6-bisphosphate to glyceraldehyde-3-phosphate and dihydroxyacetone phosphate, was shown to be aberrantly expressed in multiple cancer types." (PMID 31384177, 2019). "Our results demonstrate that the overabundance of ALDOA in cancer cells is associated with its moonlighting rather than catalytic functions." (PMID 31558701, 2019). "Accumulating evidence indicates that ALDOA contributes to the proliferation of cancer cells." (PMID 29764507, 2018). "Moreover, through its effects on aerobic glycolysis, ALDOA is able to alter the microenvironment of cancer and thus impair the regulation of cyclin D1 transcription." (PMID 29764507, 2018). "Recently, a new role of ALDOA in several cancers has been proposed." (PMID 28191039, 2017). "Although ALDOA is localized primarily in the cytoplasm, nuclear localization of ALDOA might be a common feature of proliferating cells, including cancer cells." (PMID 28191039, 2017). "Recently, increasing evidences have shown that ALDOA could express in cancer cells, and its contribution to carcinogenesis in some tumors has been proposed both in vivo and in vitro." (PMID 28191039, 2017). "Only aldolase A (ALDOA) was found to be both less oxidized on its potentially critical cysteine (Cys339) and at the same time to be more abundant, which may corroborate its critical role in cancer survival and metastasis." (PMID 40461450, 2025). "Thus, the regulatory mechanism of ALDOA presented here could have significant implications for the development of novel broad-based anti-cancer therapies." (PMID 40708574, 2025). "Interestingly, ALDOA has been found in the nuclear localization of several kinds of cancer cells." (PMID 40708574, 2025). "Pseudo-time analysis suggested that CAFs with high ALDOA and CXCL12 expression represent terminal subtypes differentiated from normal fibroblasts, indicating that during the malignant progression of cancer, normal fibroblasts transform into activated cancer-associated fibroblasts." (PMID 41584584, 2025).
cancer (continued). "In BC, mutations in the ALDOA gene have been found to be more frequent than in other types of cancer, although they may not be associated with the clinical condition." (PMID 39684297, 2024). "Thus, in addition to being diagnostic markers, these molecules may also regulate FBP1 and ALDOA during cancer progression." (PMID 35404841, 2022). "To the best of our knowledge, this study is the first to elucidate the mechanisms that underlie the anti-cancer properties of MSPA, which we reveal were mediated through the simultaneous suppression of key enzymes in glycolysis and the tricarboxylic acid cycle, namely ALDOA, ENO1, and FH." (PMID 34681284, 2021). "Therefore, a more precise classification for specific cancer types that depend on ALDOA and downstream signaling may be an important direction for further research." (PMID 35127525, 2021). "Indeed, ALDOA was reported to be the main isoform expressed in most cancer types." (PMID 30430110, 2018). "Survival heatmaps illustrate the hazard ratios (HR) of ALDOA expression for overall survival (OS), disease-specific survival (DSS), and progression-free interval (PFI) across various cancer types." (PMID 41239433, 2025). "Our study demonstrated that ALDOA is a vital driver for HCC development by activating c-Jun-mediated oncogene transcription, opening additional avenues for anti-cancer therapies." (PMID 40708574, 2025). "Protein expression analysis of ALDOA, using CPTAC datasets, also shows significantly elevated levels in multiple cancer types." (PMID 41239433, 2025). "Consequently, the excessive expression of ALDOA in HCC may be linked to noncatalytic mechanisms that facilitate cancer progression." (PMID 40708574, 2025). "Among all cancer types, LUSC demonstrated one of the highest levels of ALDOA expression, and its clinical significance was further validated through multiple datasets." (PMID 41239433, 2025). "Essential targets in therapeutic targeting of cancer metabolism are glycolytic enzymes, including LDHA, PKM2, HK2, ALDOA, G6PD, PPP cycle, glutamine serine metabolism and pyruvate oxidation." (PMID 40076506, 2025). "Among these, ALDOA induces the expression of hypoxia-inducible factor-1α (HIF-1α), leading to typical EMT-like morphological changes in cancer cells, including a transition from cuboid to spindle shape and loss of microvilli." (PMID 38577616, 2024). "In this study, the expression levels of ALDOA and p-AKT were detected in cancer tissues and paired normal tissues, and it was found that they were significantly increased in CRC tissues, and their high expression indicated poor prognosis." (PMID 38499636, 2024). "LIPH catalyzes the conversion of PA to LPA and facilitates cancer cell proliferation by enhancing YAP1 nuclear localization, stimulating the PI3K/AKT/HIF1A pathway, and maintaining ALDOA stability, ultimately resulting in aberrant glycolysis and tumorigenesis." (PMID 37990271, 2023). "Overall, the inverse correlation between ALDOA and FBP1 was consistent in LUAD and LIHC cancer cell lines, supporting the clinical results that FBP1 and ALDOA have an interplay and correlation." (PMID 35404841, 2022). "FBP is a particular metabolite in cancer, since both gluconeogeneic and glycolytic events require fructose-1,6-bisphosphatase 1 (FBP1) and ALDOA." (PMID 36077431, 2022). "We further screened for the endogenous expression level between ALDOA and PLD1 in various cancer types through the The Cancer Genome Atlas Program (TCGA) cohorts." (PMID 35127525, 2021). "In bladder cancer, ALDOA was reported to act as an oncogene by interacting with E-cadherin-epidermal growth factor receptor (EGFR) signaling, leading to cancer cell metastasis." (PMID 34458323, 2021). "Thereby, based on the in silico analysis, IA has greater interaction at two receptors (ALDOA and MSTG1) and suggest that it is a candidate for a multi-target cancer drug." (PMID 34771055, 2021).